DNAJB9 (DnaJ heat shock protein family (Hsp40) member B9)
Description:
Co-chaperone for Hsp70 protein HSPA5/BiP that acts as a key repressor of the ERN1/IRE1-mediated unfolded protein response (UPR) (By similarity). J domain-containing co-chaperones stimulate the ATPase activity of Hsp70 proteins and are required for efficient substrate recognition by Hsp70 proteins. In the unstressed endoplasmic reticulum, interacts with the luminal region of ERN1/IRE1 and selectively recruits HSPA5/BiP: HSPA5/BiP disrupts the dimerization of the active ERN1/IRE1 luminal region, thereby inactivating ERN1/IRE1 (By similarity). Also involved in endoplasmic reticulum-associated degradation (ERAD) of misfolded proteins. Required for survival of B-cell progenitors and normal antibody production (By similarity).
Synonyms: ERdj4; Mdg-1; MDG1; MST049; MSTP049
Tractability: Antibody: UniProt predicts a signal peptide or a membrane-spanning region. PROTAC: ubiquitination databases record sites on it.
Gene: Protein-coding gene on chromosome 7 (108,569,847 to 108,574,850, forward strand). Ensembl gene ENSG00000128590.
Subcellular location: Endoplasmic reticulum lumen
Subcellular location (Human Protein Atlas): Cytosol; Endoplasmic reticulum
Pathways (Reactome):
Cellular responses to stimuli: XBP1(S) activates chaperone genes
Gene Ontology:
Molecular function: misfolded protein binding; protein binding; protein-folding chaperone binding; Hsp70 protein binding
Biological process: ERAD pathway; B cell differentiation; negative regulation of IRE1-mediated unfolded protein response; positive regulation of immunoglobulin production; response to endoplasmic reticulum stress
Cellular component: endoplasmic reticulum; extracellular exosome; cytoplasm; endoplasmic reticulum lumen; endoplasmic reticulum membrane; nucleolus
Genetic constraint (gnomAD): Loss-of-function variants: 12 observed, 20.17 expected, observed/expected ratio (o/e) 0.59, 90% interval 0.38 to 0.96. The upper end of that interval is the gene's LOEUF score, 0.96, which puts it in group 4 of 6, group 1 being the genes least tolerant of losing a copy. Missense variants: 272 observed, 274.35 expected, observed/expected ratio (o/e) 0.99, 90% interval 0.9 to 1.1. Synonymous variants: 83 observed, 89.45 expected, observed/expected ratio (o/e) 0.93, 90% interval 0.78 to 1.11.
Homologues: Orthologues: chimpanzee DNAJB9 (99% identical), guinea pig DNAJB9 (96% identical), macaque DNAJB9 (96% identical), dog DNAJB9 (95% identical), pig DNAJB9 (95% identical), rabbit DNAJB9 (95% identical), mouse Dnajb9 (94% identical), rat Dnajb9 (93% identical), tropical clawed frog dnajb9 (70% identical), zebrafish dnajb9a (66% identical), zebrafish dnajb9b (57% identical), Drosophila melanogaster CG32640 (18% identical), and 1 more. Paralogues in human: DNAJB6 (33% identical), DNAJB5 (32% identical), DNAJB4 (31% identical), DNAJB1 (29% identical), DNAJB7 (28% identical), DNAJB11 (28% identical), DNAJB2 (28% identical), DNAJB8 (27% identical), DNAJB12 (25% identical), DNAJB13 (24% identical), DNAJB14 (24% identical).
Diseases named in the same sentence as DNAJB9 in open-access papers:
DNAJB9 is named in the same sentence as 60 diseases in open-access papers, as found by Europe PMC text mining. Sharing a sentence is not in itself a finding about the gene and the disease. The quoted sentences say what the papers report.
glomerular diseases (7 papers, 2020 to 2025). "DNAJB9 immunostaining has emerged as a pivotal diagnostic tool, enabling differentiation from other glomerular diseases with similar morphological features." (PMID 40747187, 2025). "Importantly, FGN patients have four-fold higher serum levels of DNAJB9 compared to controls, including patients with other glomerular diseases, and the serum DNAJB9 level is negatively associated with estimated glomerular filtration rate in the FGN cases." (PMID 33671535, 2021). "In a large clinical study that included biopsies from 84 patients with FGN, 21 with amyloidosis, 98 with other glomerular diseases, and 11 healthy controls, staining for DNAJB9 was found to have a sensitivity of 98% and a specificity of 99% for the diagnosis of FGN." (PMID 40507471, 2025). "Its absence in biopsies from patients with amyloidosis, other GN, or healthy controls established DNAJB9 as the first biomarker for FGN, allowing differentiation from amyloidosis and other glomerular diseases." (PMID 40507471, 2025). "Discussion: DNAJB9 has emerged as both a specific and sensitive biomarker in patients with FGN and has facilitated accurate differentiation from other glomerulopathies." (PMID 40559465, 2025). "In eight patients, glomerulopathy was identified, including focal and segmental glomerulosclerosis (FSGS, n = 4), membranous nephropathy (n = 3), and DNAJB9+ fibrillar glomerulonephritis (n = 1)." (PMID 35160055, 2022). "Background/Aim: Fibrillary glomerulonephritis (FGN) is a rare glomerular disease characterized by non-amyloid fibrillary deposits in the glomeruli and positive staining for DNAJB9." (PMID 40507471, 2025). "DNAJB9 staining has not been seen in other glomerular diseases including amyloidosis or in healthy subjects, and therefore is a marker for FGN with a reported 100% sensitivity and 100% specificity." (PMID 32664131, 2020). "Additionally, four of the DNAJB9-positive cases were originally diagnosed as uncertain for FGN (LM, IF, and EM features could not allow a proper distinction with an immunotactoid glomerulopathy), but presented a strong DNAJB9 expression." (PMID 36140202, 2022).
breast carcinoma (6 papers, 2021 to 2025). "Our preclinical models and clinical bioinformatics analyses have demonstrated that lower DNAJB9 expression in aggressive breast cancer than in normal breast tissues is linked to worse cancer patient outcomes." (PMID 36499297, 2022). "Using human breast cancer cell lines, preclinical models, and clinical samples, we showed that loss of DNAJB9 expression is associated with increased tumor aggressiveness and shorter OS and DMFS of patients." (PMID 33966034, 2021). "Recently, our study has revealed novel functions of DNAJB9 as a metastasis suppressor in breast cancer." (PMID 36499297, 2022). "We observed that the dysregulation of DNAJB9 related to the corresponding normal tissue controls among different tumor types, including breast tumors, indicate that DNAJB9 levels correlate inversely with the metastatic properties of breast cancer." (PMID 33966034, 2021). "To evaluate the relationship between DNAJB9 expression and clinical correlation, we further analyzed publicly available microarray datasets of patients with breast cancer in Oncomine." (PMID 33966034, 2021). "Consistent with the in vitro results, bioluminescence imaging revealed that DNAJB9 OE significantly inhibited the metastatic colonization of breast cancer into the lung." (PMID 33966034, 2021). "Using the Kaplan–Meier plotter, we observed that patients with breast cancer with high DNAJB9 expression had improved OS and DMFS (p < 0.0001)." (PMID 33966034, 2021). "First, we observed that DNAJB9 expression was significantly suppressed in metastasized breast cancer samples compared to localized breast cancer." (PMID 33966034, 2021). "Altogether, these results demonstrate that DNAJB9 governs FBXO45 expression through their interaction in breast cancer." (PMID 33966034, 2021). "Analysis of 52 breast cancer cell lines using the GEO dataset (GSE41313) revealed that DNAJB9 transcripts were reduced in highly aggressive TNBC cell lines (basal A and B) compared to the less-aggressive luminal cell lines." (PMID 33966034, 2021). "The DNAJB9 gene is reportedly one of the prognostic biomarkers of breast cancer." (PMID 36268046, 2022). "Moreover, overexpression of DNAJB9 in highly metastatic breast cancer cells showed a more spherical cell morphology, reduced expression levels of mesenchymal markers, and metastatic abilities." (PMID 36499297, 2022). "To evaluate whether DNAJB9 could functionally regulate metastasis of breast cancer cells, we established the DNAJB9-KD or DNAJB9-OE MCF7 or MDA-MB-231 cells, respectively." (PMID 33966034, 2021). "Next, we examined whether DNAJB9 expression could predict the tumor stage (T stage) of breast cancer." (PMID 33966034, 2021). "Taken together, our results demonstrated that DNAJB9 is lost in high-grade and aggressive breast cancers, is positively correlated with patient survival, and may act to suppress breast cancer progression and metastasis." (PMID 33966034, 2021). "Moreover, DNAJB9 is downregulated in TNBC tissues, and low expression of DNAJB9 predicts the aggressive phenotype of breast cancer cells and poor prognosis." (PMID 33966034, 2021). "However, the level of DNAJB9 mRNA was positively correlated with that of E-cadherin mRNA in 455 breast cancer samples (R = 0.092; p < 0.05)." (PMID 33966034, 2021). "As expected, DNAJB9 was negatively correlated with the tumor stage of breast carcinoma tissue." (PMID 33966034, 2021). "Second, a series of functional analyses using in vitro and in vivo experiments suggested that DNAJB9 could function as a tumor suppressor by inhibiting the migration and invasion of breast cancer cells and suppressing metastasis in xenograft models." (PMID 33966034, 2021). "Finally, we also characterized the mechanism by which DNAJB9 regulates breast cancer cell invasion and metastasis by regulating ZEB1 and the EMT process." (PMID 33966034, 2021).
breast carcinoma (continued). "Furthermore, data from LinkedOmics showed that the protein expression of FBXO45 was positively correlated (R = 0.129; p < 0.0001) with DNAJB9 protein expression in 102 breast cancer tissue samples." (PMID 33966034, 2021). "However, the cellular function of DNAJB9 in development and metastasis of breast cancer remains largely unknown." (PMID 33966034, 2021). "Clinically, the reduction of DNAJB9 expression, concomitant with decreased FBXO45 abundance in breast cancer tissues, correlates with poorer clinical outcomes of patients with breast cancer." (PMID 33966034, 2021). "Therefore, whether DNAJB9 is involved in the EMT process in breast cancer was confirmed." (PMID 33966034, 2021). "Collectively, these results indicate that DNAJB9 acts as a novel negative regulator of EMT and metastasis of breast cancer cells." (PMID 33966034, 2021). "Because DNAJB9 modulated the FBXO45-mediated negative regulation of ZEB1, we further investigated whether DNAJB9 and FBXO45 affect the metastasis of breast cancer." (PMID 33966034, 2021). "Intriguingly, we discovered a negative correlation between ZEB1 and DNAJB9 protein levels in 75 breast cancer tissue samples (R = −0.09855; p < 0.0001)." (PMID 33966034, 2021). "In breast cancers, the DNAJB9/MDG1/ERdj4 mRNA level is lower than that in normal breast tissues, which is correlated with poor clinical outcomes." (PMID 34948322, 2021). "Mechanistically, DNAJB9 can interact with FBXO45 (F-box/SPRY domain-containing protein 1) ubiquitin ligase to promote FBXO45 protein stability, which reduces the abundance of ZEB1 by proteasomal degradation, leading to repressed EMT, invasion, and metastasis of breast cancer cells." (PMID 36499297, 2022). "However, the modulation of DNAJB9 expression did not affect the proliferative capacity of breast cancer cells." (PMID 33966034, 2021). "Importantly, given that DNAJB9 and FBXO45 are tightly correlated in patients with breast cancer, our findings highlight DNAJB9 as a potential biomarker for predicting patient survival and a novel therapeutic target for treating patients with breast cancer." (PMID 33966034, 2021). "Our results demonstrate that DNAJB9 is an indispensable regulator for FBXO45 and that the DNAJB9–FBXO45–ZEB1 signaling axis may not only serve as a prognostic marker but also provide opportunities for developing therapeutic interventions in metastatic breast cancers." (PMID 33966034, 2021). "The roles of the DNAJB9, CHAC1, HERPUD1 genes in senescence induction have not been reported but these genes are all involved in tumorigenesis in breast cancers." (PMID 39466820, 2024).
amyloidosis (4 papers, 2020 to 2025). A disorder characterized by the localized or diffuse accumulation of amyloid protein in various anatomic sites. "The Mayo Clinic study showed that DNAJB9 was present in all 24 cases of FGN; whereas, its absence was observed in 145 cases of amyloidosis, 72 cases of other GN, and the 12 healthy controls." (PMID 40507471, 2025). "FGN mimics amyloidosis with fibrillary deposits but is distinguished by negative Congo red staining (~15-25 nm) and markers such as DNAJB9." (PMID 40821257, 2025). "The co-localization of DNAJB9 and IgG was also found in the mesangium and glomerular basement membrane, with DNAJB9 also found in FGN fibrils but not in fibrils associated with amyloidosis or immunotactoid GN." (PMID 40507471, 2025). "However, the immunohistochemical staining of these samples revealed abundant expression of DNAJB9 and the absence of a proteomic signature of amyloidosis, thus aiding the diagnosis of FGN." (PMID 40761955, 2025).
Obesity (4 papers, 2017 to 2023). Accumulation of substantial excess body fat. "TOMM5 and DNAJB9 have been reported to be involved in the development of cancer, type 2 diabetes mellitus, and obesity; however, few studies of TOMM5 and DNAJB9 on IVDD have been reported." (PMID 38041088, 2023). "As a first step to define the potential of IXA4 to improve metabolic parameters in obesity, we treated primary mouse hepatocytes with IXA4 and measured expression of Xbp1s and the XBP1s target gene Dnajb9/Erdj4." (PMID 35105890, 2022).
cystic fibrosis (3 papers, 2019 to 2025). Autosomal recessive disorder caused by pathogenic variants in the CFTR gene (cystic fibrosis transmembrane conductance regulator), which encodes a chloride and bicarbonate channel expressed in epithelial cells, and follow the diagnosis criteria. "In addition, DNAJB9 is involved in the degradation of cystic fibrosis-associated proteins as a tubulointerstitial co-chaperone and is a therapeutic target in cystic fibrosis nephritis." (PMID 41105646, 2025). "As a result, DNAJB9 could be used as a therapeutic target for cystic fibrosis." (PMID 36499297, 2022).
Hepatic steatosis (3 papers, 2015 to 2021). Steatosis is a term used to denote lipid accumulation within hepatocytes. "Indeed, overexpression of DNAJB9/MDG1/ERdj4 in the liver improves insulin sensitivity, restores protein synthesis, and reduces hepatic steatosis and adiposity in obese mouse models." (PMID 34948322, 2021).
triple-negative breast carcinoma (3 papers, 2021 to 2025). An invasive breast carcinoma which is negative for expression of estrogen receptor (ER), progesterone receptor (PR), and human epidermal growth factor receptor 2 (HER2). "In this study, we found that ectopic restoration of DNAJB9 inhibits the migration, invasion, in vivo metastasis, and lung colonization of triple-negative breast cancer (TNBC) cells." (PMID 33966034, 2021).
acute myeloid leukemia (2 papers, 2021 to 2022). Acute myeloid leukemia (AML) is a group of neoplasms arising from precursor cells committed to the myeloid cell-line differentiation. "DNAJB9 has been recently identified as the target gene of miR-32 in acute myeloid leukemia (AML)." (PMID 36499297, 2022).
Insulin resistance (2 papers, 2017 to 2020). Increased resistance towards insulin, that is, diminished effectiveness of insulin in reducing blood glucose levels. "The endoplasmic reticulum stress-related genes (DNAJB9, DNAJC3) and those involved in insulin resistance (PRKCε) were all strongly upregulated in NAFLD patients." (PMID 32429478, 2020).
breast tumors (1 paper, 2021). "In line with our preclinical studies, DNAJB9 was consistently lower in breast tumor samples than in normal breast tissue." (PMID 33966034, 2021). "Next, we examined the expression level of DNAJB9 in 26 cases of paraffin-embedded human breast tumor specimens using IHC staining." (PMID 33966034, 2021).
crescentic glomerulonephritis (1 paper, 2020). A histopathologic term for a pattern of diseases characterized by extensive crescent formation in the glomeruli; patients present clinically with rapid deterioration of renal function, and possible progression to end-stage renal failure within weeks or months. "Thus, in ANCA-positive crescentic glomerulonephritis, immunohistochemical assessments for immunoglobulins and DNAJB9, as well as electron microscopy, are important to correctly diagnose FGN." (PMID 32274231, 2020).
glioma (1 paper, 2023). A benign or malignant brain and spinal cord tumor that arises from glial cells (astrocytes, oligodendrocytes, ependymal cells). "As target genes of three branches, DDIT3 (CHOP) and DNAJB9 (IRE1α-XBP1), but not SEL1L (ATF6) were obviously upregulated in glioma cells after treatment of S4, which declared ATF6 was not the main activated branch." (PMID 37386564, 2023).
glomerulonephritis (1 paper, 2024). A renal disorder characterized by damage in the glomeruli. "Nevertheless, the primary immunofluorescence with a positive staining for DNAJB9 would be highly specific for fibrillary glomerulonephritis." (PMID 39618600, 2024).
leukemia (1 paper, 2017). A malignant (clonal) hematologic disorder, involving hematopoietic stem cells and characterized by the presence of primitive or atypical myeloid or lymphoid cells in the bone marrow and the blood. "DnaJB9 overexpression was found to increase hematopoietic stem cell repopulation capacity and Hsp70 inhibitors have anti-leukemic activity, but the participation of other DnaJ proteins in hematopoiesis or leukemia has not been explored." (PMID 28742844, 2017).
lung disease (1 paper, 2019). "It is found that DNAJB9 was one of the highly expressed genes in human nasal epithelial cells, and compared to patients with mild lung disease, patients with severe lung disease were associated with higher DNAJB9 expression." (PMID 31285458, 2019).
nephritis (1 paper, 2023). Inflammation of renal tissue. "DNAJB9-positive tubulointerstitial-predominant fibrillary nephritis was reported recently, which showed focal linear staining with IgG and fibrillar deposits along TBMs." (PMID 37596523, 2023).
nodular sclerosis (1 paper, 2025). "Additionally, while diabetic patients often show mesangial expansion and nodular sclerosis, the presence of fibrillary deposits and DNAJB9 positivity confirms the diagnosis of FGN." (PMID 40747187, 2025).
Stroke (1 paper, 2019). Sudden impairment of blood flow to a part of the brain due to occlusion or rupture of an artery to the brain. "For the activation of the IRE1α branch of UPR after stroke, mRNA levels of Xbp1s and Dnajb9 were measured in GRINA-deficient and wildtype primary murine cortical cells using RT-qPCR." (PMID 31683519, 2019). "To determine the activation of the most conserved IRE1α-XBP1 pathway after stroke, we measured spliced Xbp1 mRNA (Xbp1s) and mRNA levels of its downstream target gene Dnajb9 using RT-qPCR and performed an Xbp1s splicing detection assay." (PMID 31683519, 2019).